SMIM10L3 (small integral membrane protein 10 like 3)
Synonyms: SAGSIN1; C7orf70
Gene: Protein-coding gene on chromosome 7 (6,329,411 to 6,348,967, reverse strand). Ensembl gene ENSG00000286075.
Homologues: Orthologues: rabbit SMIM10L3 (100% identical), guinea pig SMIM10L3 (99% identical), mouse Smim10l3 (99% identical), chimpanzee FAM220A (94% identical), chimpanzee SMIM10L3 (94% identical), pig SMIM10L3 (93% identical), zebrafish smim10l3 (69% identical). Paralogues in human: SMIM10L2A (87% identical), SMIM10L2B (87% identical), SMIM10 (72% identical), SMIM10L1 (66% identical).